NLRP3 (NLR family pyrin domain containing 3)
Diseases named in the same sentence as NLRP3 in open-access papers (continued):
Sharing a sentence is not in itself a finding about the gene and the disease.
autoimmune disease (160 papers, 2012 to 2026). A disorder resulting from loss of function or tissue destruction of an organ or multiple organs, arising from humoral or cellular immune responses of the individual to their own tissue constituents. "Excessive activation of the NLRP3 inflammasome is linked to the development of various autoimmune diseases, underscoring the importance of maintaining its activity within a regulated range." (PMID 40948742, 2025). "NLRP3 is an inflammasome sensor protein that senses many pathogens and is associated with the occurrence and development of autoinflammatory and autoimmune diseases." (PMID 39873509, 2025). "While essential for pathogen defense, dysregulated NLRP3 activity is associated with various inflammatory and autoimmune diseases, such as arthritis, cardiovascular disease, and neurodegenerative disorders." (PMID 40688353, 2025). "In this regard, with aging there is an increase in pro-inflammatory cytokines, including IL-6, TNFα and NLRP3 inflammasome, which are associated with age-related diseases such as autoimmune diseases, cancer, and metabolic disorders." (PMID 38265117, 2024). "Understanding the intricate mechanisms of the NLRP3 inflammasome and its associated components is crucial for developing targeted therapies against inflammatory and autoimmune diseases." (PMID 38893506, 2024). "NLRP3 inflammasome activity must be controlled as unregulated and chronic inflammation underlies inflammatory and autoimmune diseases." (PMID 39117604, 2024). "Previous studies have demonstrated that genetic polymorphism of NLRP3 was associated with susceptibility to autoimmune diseases." (PMID 36673016, 2023). "Taking this evidence together, NLRP3 polymorphisms are related to autoimmune diseases and the activation of inflammasome." (PMID 36673016, 2023). "Experimental autoimmune uveitis, an experimental autoimmune disease, has been proved to associate with NLRP3 inflammasome." (PMID 37817895, 2023). "Genetic polymorphisms of NLRP3 are related to the disease susceptibility and severity of several autoimmune diseases." (PMID 36673016, 2023). "In conclusion, we have shown that NLRP3 polymorphisms play a critical role in the pathogenesis of autoimmune diseases." (PMID 36673016, 2023). "The genetic polymorphisms of NLRP3 have been observed to serve a vital role in the disease susceptibility and severity of different autoimmune diseases." (PMID 36673016, 2023). "NLRP3 polymorphisms play a vital role in the pathogenesis of autoimmune diseases, and that disease severity can be partially explained by the activity of NLRP3 inflammasome." (PMID 36673016, 2023). "Numerous studies have demonstrated that the development of several autoimmune disorders is linked to the disruption of NLRP3 inflammasome activation." (PMID 37960237, 2023). "One intriguing aspect of the action of NPT1220-312 relates to the NLRP3 inflammasome, a multimolecular complex implicated in a wide range of neurodegenerative and autoimmune disorders." (PMID 35265316, 2022). "As a result, dysregulation of the NLRP3 inflammasome has been linked to the advancement of a number of inflammatory and autoimmune disorders, including neurodegenerative diseases like Alzheimer’s, Parkinson’s, and amyotrophic lateral sclerosis." (PMID 35514993, 2022). "NLRP3 mutations have been reported to lead to many autoimmune disorders, but only a few disease-causing variants are associated with T1D." (PMID 35528000, 2022). "The NLRP3 inflammasome is linked with the sensitivity, disease severity, and treatment outcomes of autoimmune disorders." (PMID 36387275, 2022). "There is a prevailing notion that that high expression of NLRP3 inflammasome is observed in patients with autoimmune diseases; thus, the NLRP3/IL-1 axis is highly susceptible to initiate an overreaction of the immune system." (PMID 35693810, 2022).
autoimmune disease (continued). "Another autoimmune disease related to NLRP3 mutations are known as CAPS, including familial cold autoinflammatory syndrome (FCAS), Muckle-Wells syndrome, and neonatal-onset multisystem inflammatory disease (NOMID)." (PMID 35774778, 2022). "The existing knowledge about the association between NLRP3 rs35829419/rs10754558 polymorphisms and susceptibility to autoimmune diseases (AIDs) remains controversial." (PMID 34367252, 2021). "NLRP3 mutations can lead to juvenile idiopathic arthritis, rheumatoid arthritis and autoimmune diseases such as familial Mediterranean fever clinical commonly used drugs." (PMID 34526897, 2021). "Ca2+ flux-triggered NLRP3 inflammasome activation is closely associated with the pathogenesis of several human autoimmune diseases." (PMID 33850310, 2021). "Excessive activation of NLRP3 inflammasome has been implicated in the initial phase of numerous autoinflammatory and autoimmune diseases including EAM." (PMID 34603042, 2021). "Among inflammasomes, nucleotide-binding domain (NLR) and pyrin domain-containing receptor 3 (NLRP3) has been linked with many inflammatory and autoimmune diseases." (PMID 34445484, 2021). "The causative role of NLRP3 in innate immune responses associated with human health and the progression of autoinflammatory and autoimmune diseases has compelled a growing interest in the pharmacological mediation of NLRP3-associated inflammation." (PMID 33036374, 2020). "The activation of NLRP3 by cellular stress leads to activation of the inflammasome which is associated with a number of autoinflammatory syndromes and autoimmune diseases." (PMID 32371954, 2020). "The NLRP3 inflammasome has been associated with several human inflammatory and autoimmune diseases and represents a potential therapeutic target for disrupting IL-1β production." (PMID 30894604, 2019). "A similar approach targeting IL-1β was successfully applied to treat NLRP3 inflammasome associated autoimmune diseases and cancer." (PMID 31118894, 2019). "Dysregulation of this inflammasome has been linked to several autoimmune diseases, indicating that NLRP3 is tightly regulated to prevent aberrant activation." (PMID 31866999, 2019). "Our finding that PTPN22 polymorphism has a dual role in the development of autoimmune diseases is of particular interest as recent studies showed that NLRP3 activation is negatively regulated by tyrosine phosphorylation." (PMID 30915320, 2019). "By driving both innate and adaptive immune responses, the NLRP3 inflammasome is linked to the pathogenesis of various autoimmune diseases, including type 1 diabetes, cystic fibrosis, rheumatoid arthritis, autoimmune colitis, psoriasis, systemic lupus erythematosus, and systemic sclerosis." (PMID 40948742, 2025). "Dysregulation of the NLRP3-caspase-1-IL-1β/IL-18 axis has been implicated in various inflammatory conditions, autoimmune diseases, and infections, highlighting the importance of understanding the intricacies of NLRP3 inflammasome regulation in immune homeostasis." (PMID 40040812, 2025). "Even though the inflammasome seems to be an optimal target to treat autoimmune diseases and reduce associated CV, drugs that target the NLRP3 inflammatory pathway can have serious adverse effects, such as an increased risk of infection (anakinra, canakinumab and tofacitinib)." (PMID 38929699, 2024). "Next, we explored whether UBXN6 deficiency modulated the activation of the NLRP3 inflammasome, which is critical for the innate defense of patients with autoinflammatory and autoimmune diseases." (PMID 39438692, 2024). "There are, indeed, some heritable forms of ColdU, named CAPS (cryopyrin-associated autoinflammatory syndromes) which are rare autoimmune disorders characterized by an IL-1b overproduction determined by mutations in the gene NLR family pyrin domain containing 3 (NLRP3)." (PMID 37873787, 2023). "The NLRP3 gene is reportedly associated with several autoimmune diseases." (PMID 35528000, 2022).
autoimmune disease (continued). "NLRP3 inflammasome, which is activated upon signs of cellular “danger” to trigger innate immune defense through the maturation of pro-inflammatory cytokines such as IL-1β and IL-18, is reported to be closely associated with autoimmune diseases." (PMID 35965334, 2022). "More recent studies indicate that NLRP3 variations may be associated with several autoimmune diseases including neonatal-onset multisystem inflammatory disease (NOMID) and Behcet's disease (BD)." (PMID 34790822, 2021). "The NLRP3 inflammasome activates pathways and their associated products and plays an important role in the development of various inflammatory responses and metabolic and autoimmune diseases." (PMID 33954183, 2021). "Increasing experiments show that NLRP3 inflammasome may play different pathogenic roles in autoimmune diseases, which provides a promising therapeutic option for autoimmune diseases." (PMID 34707607, 2021). "However, the same cytokines produced following NLRP3 activation are also associated with exuberant inflammation and autoimmune disorders, illustrating both the protective and pathogenic effects of NLRP3." (PMID 32098318, 2020). "In addition, circ003593 inactivated the NLRP3 complex, which is the best characterized inflammasome complex and has been linked with various human autoinflammatory and autoimmune diseases." (PMID 33101012, 2020). "Further studies are required to investigate whether the downregulation of the NLRP3 inflammasome is an outcome or cause of the progression of autoimmune disorders." (PMID 32973739, 2020). "The NLRP3 inflammasome must be well orchestrated to prevent the aberrant activations under physiological and pathological conditions, because uncontrolled activation of NLRP3 inflammasome is one of the major causes of a variety of autoimmune diseases and metabolic disorders." (PMID 30349539, 2018). "The activation of NLRP3 inflammasome is associated with the pathogenesis of autoimmune diseases." (PMID 27250627, 2016). "As recent studies suggested the important role of NALP1 and NALP3 genes in the predisposition to autoimmune disorders, we evaluated the possible association of single nucleotide polymorphisms (SNPs) in NLRP1 and NLRP3 genes in celiac patients and in healthy individuals." (PMID 23658628, 2013). "As NLRP3 is associated with numerous autoinflammatory and autoimmune diseases, understanding how NLRP3 is regulated will be necessary for understanding and potentially preventing disease development, as well as for the design of inhibitors which are useful under specific inflammatory conditions." (PMID 24062750, 2013). "Hence, NLRP3 inflammasome and associated cytokines may participate in the pathogenesis of autoimmune diseases-related ILD." (PMID 38203796, 2024). "The NLRP3 gene encodes a protein that is part of the NLRP3 inflammasome complex, which plays a crucial role in regulating the body’s inflammatory response and is implicated in the development of various conditions, including autoimmune disorders and auto-inflammatory diseases." (PMID 39061976, 2024). "Inflammasomes are important regulators of immunity and inflammatory diseases, making NLRP3 one of the most attractive targets for the development of innovative therapeutic approaches due to its association with several human inflammatory and autoimmune diseases." (PMID 35890124, 2022). "In addition, increased caspase-1 activation and IL-1β production by the constitutively active autoimmune disease-associated variants of NLRP3 were also linked to autoimmune diseases, indicating a crucial need for appropriate NLRP3 activation and IL-1β production." (PMID 35246034, 2022). "The new role of the NLRP3 inflammasome and the mTOR pathway as regulators of IL-1β and IgM in activated B-lymphocytes studied here offers a potential new strategy to treat autoimmune disease in which IL-1β and pathogenic IgM antibodies may play a role, particularly if triggered by infectious agents." (PMID 29170665, 2017).
autoimmune disease (continued). "Thus, TRIM31 could be a potential therapeutic target for NLRP3-associated syndromes, including autoinflammatory and autoimmune diseases." (PMID 27929086, 2016). "Evidence increasingly underscores the centrality of HMGB1 and NLRP3 in promoting chronic inflammation and multi-organ damage across a spectrum of diseases, including autoimmune disorders, trauma, and stress." (PMID 40688353, 2025). "Further investigation is needed to elucidate the mechanistic relationships between NLRP3 inflammasome signaling and DAMPs in diverse autoimmune diseases." (PMID 40948742, 2025). "This drug has been widely considered as an anti-inflammatory alternative to treat NLRP3 induced inflammation, including in autoinflammatory and autoimmune diseases." (PMID 40854880, 2025). "Mechanistically, the NLRP3 inflammasome serves as a key checkpoint in both innate and adaptive immunity during the development of autoimmune diseases." (PMID 40948742, 2025). "Multiple studies have shown that overactivation of the NLRP3 inflammasome results in excessive inflammation and tissue damage, leading to pathological conditions that contribute to autoimmune diseases." (PMID 40948742, 2025). "Understanding the role of the HMGB1/NLRP3 signaling pathway is especially pertinent for systemic diseases such as autoimmune disorders, cardiovascular conditions, and neurodegenerative diseases." (PMID 40688353, 2025). "Future studies are needed to elucidate the molecular interaction between autophagy and the inflammasome to provide insights for developing autophagy-based treatments for NLRP3-related inflammatory and autoimmune diseases." (PMID 40307577, 2025). "The NLRP3 inflammasome plays a crucial role in autoimmune disorders by regulating inflammatory responses and promoting the production of inflammatory cytokines, contributing to pathophysiological signatures in different autoimmune disorders." (PMID 38666950, 2024). "NLRP3 inhibitors have been investigated as potential drugs for the treatment of various inflammatory and autoimmune diseases." (PMID 38892264, 2024). "Such is the case of MALT lymphoma development in the setting of autoimmunity, where NLRP3 inflammasome activation was mainly investigated in the setting of SS, an autoimmune disease correlating with lymphomagenesis due to chronic antigenic stimulation." (PMID 38397043, 2024). "The upregulated NLRP3 triggered canonical pyroptosis and apoptosis, and also induced the release of proinflammatory cytokines in autoimmune diseases, implying its promising therapeutic potential." (PMID 38224186, 2024). "The compelling importance of NLRP3 as a target for the treatment of inflammatory and autoimmune diseases highlights the urgent need to develop highly specific and potent NLRP3 inflammasome inhibitors with as few adverse effects as possible." (PMID 38666950, 2024). "Cumulative studies have confirmed that NLRP3 plays an important role in regulating innate immunity and autoimmune diseases, and its inhibitors have shown good efficacy in animal models of various inflammatory diseases." (PMID 38849934, 2024). "Overall, the use of miRNAs as NLRP3 inhibitors holds promise as a potential therapeutic approach for treating a range of inflammatory and autoimmune diseases." (PMID 38892264, 2024). "Increasing evidence emphasizes the importance of NLRP3 inflammasome activation, caspase-1 activation, and IL-1β release in the development of autoimmune diseases such as systemic lupus erythematosus, multiple sclerosis, and ulcerative colitis." (PMID 39723212, 2024). "The active NLRP3 inflammasome not only stimulates pyroptosis but also apoptosis, thereby participating in the pathogenesis of autoimmune diseases by inducing inflammation of monocytes." (PMID 38224186, 2024). "Previous studies reported that autoantibodies activated the activity of NLRP3 inflammasome and exacerbated the severity of autoimmune diseases." (PMID 36673016, 2023).
autoimmune disease (continued). "NLRP3 has been considered to be related to autoimmune diseases, tumors and, of course, coronary atherosclerosis." (PMID 37214347, 2023). "Shen 2018 discussed the involvement of NLRP3 in autoimmune diseases, including SLE, and proposed it as a potential therapeutic target." (PMID 37312878, 2023). "Particularly in the last three years, a large number of bioactive substances regulating the NLRP3 inflammasome for treating autoimmune diseases have been gradually discovered, and their therapeutic effects have been tested in various animal models." (PMID 37960237, 2023). "In recent years, a number of bioactive substances have shown new potentiality for regulating the NLRP3 inflammasome in autoimmune diseases." (PMID 37960237, 2023). "Nevertheless, an overabundance of NLRP3 inflammasome activation can contribute to the advancement of diverse inflammatory disorders, including the autoimmune diseases referenced in the following subsection." (PMID 37960237, 2023). "The activation of NLRP3 inflammasome leads to the stimulation of cytokines and is significantly involved in the pathogenesis and progression of autoimmune diseases." (PMID 36673016, 2023). "Dysregulation of NLRP3 and the NLRP3 inflammasome has been found in the pathogenesis of various diseases, including autoimmune diseases and neurodegenerative diseases." (PMID 37649483, 2023). "Several gain-of-function mutations in the NLRP3 inflammasome have been suggested to induce spontaneous activation of NLRP3 and hence contribute to development and disease severity in numerous autoinflammatory and autoimmune diseases." (PMID 38077364, 2023). "Numerous infectious and autoimmune diseases are attributed to abnormal intrinsic dysregulation of the NLRP3 inflammasome machinery." (PMID 37854633, 2023). "Recently, the therapeutics development of autoimmune diseases has been designated to target NLRP3 inflammasome." (PMID 36673016, 2023). "Especially in recent years, extracellular IL-37 has been confirmed to exert a regulatory role in autoimmune disease by inhibiting the activation of NLRP3 inflammasome." (PMID 36418383, 2022). "MCC950 is a potent, selective small molecule inhibitor of NLRP3, and its therapeutic effects on various autoimmune diseases have recently been anticipated." (PMID 34270818, 2022). "Aberrant NLRP3 inflammasome activation is considered to be responsible for the autoimmune disease CAPS, caused by the gain of function mutant of NLRP3." (PMID 36741414, 2022). "Extracellular IL-37 has been confirmed to exert a regulatory role in autoimmune disease by inhibiting the activation of NLRP3 inflammasome." (PMID 36418383, 2022). "Although multiple models of NLRP3 inflammasome activation have been identified in autoimmune diseases, the most common model comprises NLRP3 inflammasome activation with ROS production." (PMID 35958572, 2022). "Recent studies have demonstrated a strong link between NLRP3/caspase-1/IL-1β axis and some autoimmune diseases including multiple sclerosis, systemic lupus erythematosus and ulcerative colitis." (PMID 35965334, 2022). "NLRP1 and NLRP3 inflammasomes are the best characterized and they have been related to several autoimmune diseases." (PMID 35457026, 2022). "NLRP3 activation that is dysregulated worsens a variety of inflammatory and autoimmune diseases, as well as neurodegenerative diseases." (PMID 35514993, 2022). "There is increasing evidence that aberrant activation of the NLRP3 inflammasome and downstream inflammatory pathways play an important part in the pathogenesis of multiple autoimmune diseases, including LN." (PMID 34489689, 2021). "NLRP3 inflammasome is significantly increased in autoimmune diseases such as T1D, IBD, SLE, RA, SSC, psoriasis, and AITDs." (PMID 34707607, 2021). "The dysregulation of NLRP3 inflammasome activation leads to several autoimmune diseases such as multiple sclerosis (MS) and experimental autoimmune encephalomyelitis (EAE)." (PMID 34445484, 2021).